KLF5 (KLF transcription factor 5)
Diseases named in the same sentence as KLF5 in open-access papers (continued):
Sharing a sentence is not in itself a finding about the gene and the disease.
colorectal cancer (continued). "miR-4711-5p was also shown to bind directly to the 3′UTR of KLF5, thereby suppressing colorectal cancer cell proliferation, migration, and stemness in vitro and inhibiting tumor growth in vivo in mouse models." (PMID 37173904, 2023). "In this study, we aimed to explicate a regulatory mechanism of the KLF5 gene product from a view of three-dimensional genome structure in colorectal cancer (CRC)." (PMID 34707247, 2022). "In gastrointestinal cancers, including gastric cancer and colorectal cancer, KLF5 was predominantly amplified." (PMID 33923166, 2021). "KLF5 functions as a transcription factor and regulates the diverse protein-coding genes (PCGs) in colorectal cancer (CRC)." (PMID 32943987, 2020). "Further, we propose that Krüppel‐like factor 5 (KLF5), the downstream effector of this pathway, promotes cisplatin/oxaliplatin resistance supporting metastasis in colorectal cancer patients." (PMID 30478887, 2019). "We next examined changes in PrPC, FOXO3a, and KLF5 expression levels during progression from primary colorectal cancer to liver metastasis in matched patient samples, to determine a signaling response to platinum‐based therapy." (PMID 30478887, 2019). "ML264, a small molecule inhibitor of KLF5, potently inhibits proliferation of colorectal cancer cells." (PMID 29348684, 2018). "For example, KLF5 has been identified as a therapeutic target in colorectal cancer, and a small molecule, compound CID 5951923, which specifically inhibits KLF5 expression, has been developed through high throughput screening." (PMID 25170806, 2014). "In this campaign, the investigators are attempting to identify small molecule inhibitors of Krüppel-like factor 5 (KLF5), as studies showed that KLF5 inhibition reduces proliferation of human colorectal cancer cells and intestinal tumor formation in mice." (PMID 23155465, 2012). "LINC00908 facilitates colorectal cancer cell proliferation via modulating the miR‐143‐3p/KLF5 axis." (PMID 40344383, 2025). "This review will focus on the roles KLF4 and KLF5 play in colorectal cancer." (PMID 37173904, 2023). "This review will focus on KLF4 and KLF5’s role in colorectal cancer (CRC) tumorigenesis." (PMID 37173904, 2023). "Therefore, we suspected that KLF5 is involved in oxaliplatin-induced apoptosis in colorectal cancer." (PMID 35379798, 2022). "For example, lncRNA TTN-AS1 could sponge miR-376a-3p to promote colorectal cancer development by regulating KLF5." (PMID 33600548, 2021). "ML264, a small‐molecule inhibitor of KLF5, exerts antiproliferative effects in colorectal cancer; however, its function in osteosarcoma remains unknown." (PMID 32285603, 2020). "Further, high KLF5 expression was observed in BRAF‐mutant colorectal cancer." (PMID 30478887, 2019). "ML264 inhibits KLF5 expression in colorectal cancer cell lines." (PMID 28437471, 2017). "However, ours is the first in which to show a critical role of Klf5 in mediating the tumorigenic effect of combined Apc and KRAS mutations, a commonly encountered scenario in colorectal cancer in humans." (PMID 20298593, 2010). "This suggests that therapies targeted to KLF5 may have potential therapeutic benefit to patients with colorectal cancer." (PMID 20298593, 2010). "Further investigation may prove KLF5 an attractive target for intervention in the prevention or treatment of colorectal cancer." (PMID 20298593, 2010). "Indeed, a recent screen for small molecule inhibitors of KLF5 expression has yielded several potent compounds that inhibit proliferation of colorectal cancer cells." (PMID 20298593, 2010). "We therefore propose that KLF5 might explain why chr13q is commonly gained and rarely lost in colorectal cancer, unlike its recurrent loss across multiple other cancer types." (PMID 38622679, 2024).
colorectal cancer (continued). "In addition, studies have shown that knockdown of KLF5 could reduce cellular resistance to adriamycin in mesenchymal thyroid cancer, while high expression of KLF5 in colorectal cancer predicted poorer neoadjuvant chemotherapy outcomes." (PMID 37063424, 2023). "KLF5 has been reported as a lineage-survival oncogene whose expression is upregulated in specific cancer types, such as squamous carcinoma (e.g., head and neck cancer, oesophageal cancer) and gastrointestinal cancer (e.g., colorectal cancer, gastric cancer, pancreatic cancer)." (PMID 34707247, 2022). "Furthermore, the direct interaction between PrPC and EGFR is determinant for cisplatin/oxaliplatin resistance in colorectal cancer cells via FOXO3a-Krüppel-like factor 5 (KLF5) signaling, thus contributing to the development of metastases and poor outcome in CRC patients." (PMID 33418999, 2021). "Its transcriptional activity was regulated by MAPK effector Egr-1, which could be activated by RTK ligands or mutant HRAS, on the other hand, both LY294002 and wortmannin, inhibitors of PI3K, could efficiently down-regulate KLF5 promoter transcriptional activity in DLD-1 colorectal cancer cells." (PMID 26544730, 2015). "According to The Cancer Genome Atlas (TCGA) database, the decreased expression of KLF5, KLHL13, and CUL3 in colorectal cancer tissues was predictive of poorer overall survival." (PMID 41443421, 2025). "Inhibiting the KLF5 (Kruppel-like factor 5)/LIF (leukemia inhibitory factor)/MTF1 (metal regulatory transcription factor 1)/FPN1 (ferroportin-1) axis induces iron overload, sensitizing colorectal cancer to oxaliplatin." (PMID 39935430, 2025). "Previous studies have demonstrated that Krupple-like factor 5 (KLF5), a zinc-finger transcriptional factor, may be a potential therapeutic target for oxaliplatin-resistant CRC (colorectal carcinoma)." (PMID 41465103, 2025). "The two top genes, which are much more essential in colorectal cancer cells than in other cancer types, were CTNNB1 and KLF5." (PMID 38622679, 2024). "In advanced colorectal cancer, mesenchymal stromal cell-derived CCL7 stimulated the acetylation of KLF5 by p300, subsequently acetylated KLF5 and transcriptionally activated CXCL5 expression to facilitate tumor metastasis." (PMID 36923542, 2023). "By targeting the KLF5/PI3K/AKT axis, this approach addresses a fundamental mechanism of chemoresistance and has the potential to significantly improve outcomes for patients with advanced colorectal cancer." (PMID 40735324, 2025). "This promoter-enhancer loop may modulate the expression of KLF5 and CCAT1, resulting in the maintenance of colorectal cancer stemness." (PMID 37173904, 2023). "Once bound to this interface, these compounds selectively suppressed levels of the KLF5 protein and reduced the expression of proteins involved in the WNT signaling pathway, thereby inhibiting the proliferation and survival of transplanted colorectal cancer cells in vivo." (PMID 37173904, 2023).
gastric cancer (36 papers, 2013 to 2025). A primary or metastatic malignant neoplasm involving the stomach. "Kruppel-like factor 5 (KLF5) is correlated with a worse prognosis of gastric cancer and is positively associated with Cyclin D1 in gastric cancer, as observed in MGC803 and SGC7901 cell lines." (PMID 36769170, 2023). "KLF5 overexpression has been discovered in gastric cancer, and it has been linked to greater tumor sizes and later tumor (T) stages." (PMID 35345512, 2022). "Intriguingly, in bladder, intestinal, breast, and gastric cancers, KLF5 is oncogenic and linked to poor prognosis, often due to activating KLF5 gene alterations." (PMID 34737261, 2021). "Since H. pylori increases the risk for gastric cancer and KLF5 mediates oncogenic pathways in the gastrointestinal tract, the aim of this study was to define the role of KLF5 in H. pylori-induced gastric inflammation and injury." (PMID 23372710, 2013). "KLF5 has been previously implicated in oesophageal squamous cell carcinoma as a tumour suppressor and has been identified as pro-tumorigenic in gastric cancer via amplifications." (PMID 32880368, 2020). "KLF5 was expressed by immunohistochemistry in 45.7% of patients with localized gastric cancer undergoing curative gastrectomies in a Korean center, and this expression was associated with a trend towards better 5-year survival." (PMID 39768557, 2024). "KLF5 overexpression enhances the malignancy of gastric cancer via modulating cell cycle proteins p21 and CDK4." (PMID 37181807, 2023). "Crocin at 2–3 μM reduces the expression of HIF-1α in AGS and HGC-27 gastric cancer cells by inhibiting the miR-320/Krüppel-like factor 5 (KLF5)/HIF-1α signaling axis." (PMID 36438836, 2022). "In previous studies, miR-145-5p suppresses KLF5 expression in gastric cancer and hepatocellular carcinoma." (PMID 35836107, 2022). "The study indicated that KLF5 promoted the invasive and metastatic abilities of tumor cells by activating the CCL5/CCR5 axis in gastric cancer-associated fibroblasts." (PMID 35589690, 2022). "Several studies have found that miR-145-5p can regulate KLF5 expression in various cancers, such as cervical cancer, hepatocellular carcinoma, and gastric cancer." (PMID 35836107, 2022). "As for gastric cancer, among 441 primary tumor samples studied, 182 tumors had KLF5 amplification (41.4%), whereas 43 tumors had KLF5 deletion (9.8%)." (PMID 33923166, 2021). "For example, expression of CDKN1C, RASSF7, GPRC5A, and MPZL2 were all significantly related to KLF5 in gastric cancer tissue." (PMID 33923166, 2021). "One recent study silenced KLF5 expression using siRNAs and demonstrated that KLF5 downregulation inhibited the proliferation of gastric cancer cells." (PMID 33923166, 2021). "Then, the relationship between KLF4 and KLF5 expression levels and Helicobacter pylori infection in gastric cancer was explored." (PMID 34367275, 2021). "In gastric cancer and a subset of bladder cancer, there were duplications of chromosome 13q as well as regional amplification of a region close to KLF5." (PMID 33923166, 2021). "Using TCGA data and other public data sets, we studied the copy number variation (CNV) and gene expression of KLF5 in gastric cancer." (PMID 33923166, 2021). "Then the relation between the expression of KLF5 and these genes was assessed in human gastric cancer tissues." (PMID 33923166, 2021). "Two studies investigated the expression of KLF5 in gastric cancer samples, but arrived at different conclusions about the prognostic value of KLF5." (PMID 33923166, 2021). "To elucidate the mechanism by which KLF5 promotes proliferation and migration in gastric cancer, we next studied the expression levels of CyclinD1 and MMP9 proteins." (PMID 34367275, 2021).
gastric cancer (continued). "The expression of KLF5 in gastric cancer samples has also been studied by other investigators using immunohistochemistry." (PMID 33923166, 2021). "For instance, KLF5-activated lncRNA NEAT1 accelerated gastric cancer progression via serving as a scaffold for BRG1 to down-regulate GADD45A expression." (PMID 33931086, 2021). "One study using microarray revealed that the KLF5 gene locus was amplified in around 10% of gastric cancer." (PMID 33923166, 2021). "The discrepancy highlights the need for more studies of KLF5 in independent cohort of gastric cancer patients." (PMID 33923166, 2021). "We then tested KLF5 expression in a series of gastric cancer cell lines using RT-PCR and Western blot." (PMID 33923166, 2021). "KLF5 promotes the proliferation of gastric cancer cells and the expression of metastasis-related molecules." (PMID 34367275, 2021). "The clinical significance of KLF5 amplification and gene expression in gastric cancer were evaluated." (PMID 33923166, 2021). "While the role of KLF5 in gastrointestinal tract development and the formation of intestinal tumors has been demonstrated extensively, its function in gastric cancer is still unclear." (PMID 33923166, 2021). "In our analysis focusing on both low and high KLF5 amplifications, we found KLF5 gene was amplified in 41.4% of gastric cancer tissue from TCGA dataset." (PMID 33923166, 2021). "In gastric cancer, the poorly differentiated subtype of gastric cancer shows high expression of KLF5, and patients with high expression of KLF5 have a poor prognosis." (PMID 34367275, 2021). "KLF5 is also frequently amplified in gastric cancer and has recently been shown to regulate gene expression in OAC in combination with other transcription factors, GATA6, ELF3 and EHF." (PMID 32880368, 2020). "Additionally, NAT10 was found to increase the ability of gastric cancer cells to adhere to hepatocytes via ac4C modification of KLF5 mRNA, leading to increased transcription of ITGαV." (PMID 39985269, 2025). "Additionally, KLF5 upregulates ITGαV, facilitating gastric cancer cell attachment to hepatocytes, both contributing to gastric cancer liver metastasis." (PMID 39985269, 2025). "However, another study on gastric cancer demonstrated that crocin inhibits the EMT, migration and invasion of cancer cells obtained from biopsies of gastric cancer patients, through the miR-320/Krüppel-like factor 5 (KLF5)/HIF-1α signalling pathway." (PMID 39334719, 2024). "Current studies on KLF5 in gastric cancer have been extensive, but the role of SPI1 is still unknown." (PMID 36967718, 2023). "We found that KLF5 was highly expressed in tumors such as OC, bile duct, and gastric cancer." (PMID 37702443, 2023). "Similarly, in gastric cancer, KLF5 is frequently overexpressed and has been shown to promote cell proliferation, invasion and metastasis." (PMID 37461162, 2023). "This evidence demonstrated that KLF5 was essential for the proliferation of gastric cancer cells." (PMID 33923166, 2021). "We found that KLF5 expression varied among gastric cancer cell lines." (PMID 33923166, 2021). "We then explored the function of KLF5 in gastric cancer cell lines using KLF5 siRNAs." (PMID 33923166, 2021). "In our cohort, KLF5 mRNA was elevated in 67.6% (50/74) gastric cancer samples." (PMID 33923166, 2021). "Collectively, these data demonstrated KLF5 played an oncogene-like role in gastric cancer." (PMID 33923166, 2021). "Functional assays revealed KLF5 was essential for the proliferation of gastric cancer." (PMID 33923166, 2021). "We then performed survival analysis using TCGA dataset to see whether KLF5 had prognostic value in gastric cancer." (PMID 33923166, 2021). "The effects of KLF5 on gastric cancer cell proliferation were measured by CCK-8 assay." (PMID 34367275, 2021). "In addition, higher KLF5 expression correlated with more locally invasive gastric cancer as indicated by bigger tumor size and higher T stage." (PMID 33923166, 2021).
gastric cancer (continued). "In addition, we also observed decreased clone formation ability of gastric cancer cells when KLF5 was silenced." (PMID 33923166, 2021). "In addition, higher KLF5 expression correlated with more locally invasive gastric cancer and higher T stage." (PMID 33923166, 2021). "The function of KLF5 was studied using gastric cancer cell lines as well." (PMID 33923166, 2021). "In gastric cancers, KLF5 was suffered from arm-level as well as focal amplification." (PMID 33923166, 2021). "In this study, we tried to clarify the function of KLF5 in gastric cancer." (PMID 33923166, 2021). "Our data supported an oncogene-like role played by KLF5 in gastric cancer." (PMID 33923166, 2021). "The function of KLF5 in cell proliferation was studied in gastric cancer cell lines and organoids." (PMID 33923166, 2021). "In addition, other miR-153 downstream transcripts, such as SNAI1 or KLF5 were reported to be involved in functional modulations in gastric cancer." (PMID 32849774, 2020). "Furthermore, crocin inhibited the migration and invasion of AGS and HGC-27 gastric cancer cells by a reduced level of Krüppel-like factor 5 (KLF5), HIF-1α, and EMT activity by increasing E-cadherin and decreasing Snail and N-cadherin." (PMID 33321708, 2020). "Crocin was further found to be associated with reduced expression of Krüppel-like factor 5 (KLF5) and hypoxia-inducible factor-1α (HIF-1α), two important transcription factors for the development of gastric cancer, following administration in human gastric cancer cell lines AGS and HGC-27 cells." (PMID 33375488, 2020). "Similarly, KLF5 amplification was also reported by another study in gastric cancer." (PMID 33923166, 2021). "ELF3, together with KLF5 and EHF overexpression, has been shown to characterize a subset of peritoneal metastatic gastric cancers through the induction of super-enhancers." (PMID 41425714, 2025). "The expression of two other transcription factors, ELF3 and KLF5, also correlated with the expression of CDX2 in gastric cancer (Spearman correlation coefficient 0.21, p = 1.07 × 10−5, and Spearman correlation coefficient 5.49, p = 1.07 × 10−13, respectively)." (PMID 39768557, 2024). "Crocin up-regulates the levels of miR-320, reduces the expression of KLF5, and reduces the levels of HIF-1α, thereby inhibiting the migration, invasion, and epithelial-mesenchymal transition (EMT) of gastric cancer cells." (PMID 36438836, 2022). "As MSI status and the diffused pathological class were well-known prognostic factors for gastric cancer, we thus performed multivariate survival analysis including these factors and TNM stage to assess the prognostic value of KLF5 expression." (PMID 33923166, 2021). "Bioinformatics analysis showed that in gastric cancer and rectal adenocarcinoma, the promoter region of KLF4 and KLF5 was significantly hypomethylated." (PMID 34367275, 2021). "In univariate analysis, KLF5 expression, TNM stage and Lauren classification were significant prognostic factors for gastric cancer." (PMID 33923166, 2021). "This is in keeping with our finding that there is extensive overlap between the binding of KLF5 and GATA6 which is reinforced by recent studies that show that KLF5 binds with GATA6 in OAC and gastric cancer." (PMID 32880368, 2020). "Furthermore, crocin has been observed to modify the expression of Krüppel-like factor 5 (KLF5), hypoxia-inducible factor-1α (HIF-1α), and miR-320 in AGS and HGC-27 gastric cancer cells." (PMID 37736510, 2023). "Also, anti-proliferative activity of miR-153 is mediated by targeting Kruppel-like factor 5 (KLF5) in breast and gastric cancers." (PMID 36158686, 2022). "In gastrointestinal tumors with predominantly KLF5 amplification, including gastric cancer (STAD), colon cancer (COAD), and rectum cancer (READ), an increase in KLF5 transcripts could be observed (top 3)." (PMID 33923166, 2021). "In the two studies investing expression of KLF5 in gastric cancer tissue, no functional experiment was performed." (PMID 33923166, 2021).
gastric cancer (continued). "It was speculated that in gastric cancer and rectal adenocarcinoma, abnormal methylation in the promoter region of KLF4 and KLF5 is involved in the progression or suppression of KLF4 and KLF5." (PMID 34367275, 2021). "Five genes, e.g., DGAT2, JAKMIP1, KRT7, PGLYRP1, and TINAGL1, showed very low correlation coefficient and/or insignificant p-values, suggesting they might not be regulated by KLF5 in human gastric cancer." (PMID 33923166, 2021). "However, KLF5 expression in gastric cancer is not a meaningful prognostic factor for the patients." (PMID 33923166, 2021). "Although the relationship between KLF5 and HIF-1α in gastric cancer is not well defined, KLF5 is a known transactivator of HIF-1α in colon cancer." (PMID 33321708, 2020).